MITF (melanocyte inducing transcription factor)
Diseases named in the same sentence as MITF in open-access papers (continued):
Sharing a sentence is not in itself a finding about the gene and the disease.
hearing loss (10 papers, 2019 to 2025). "Pathogenic variations in SOX10 (96.5%) and MITF (89.6%) are more frequently linked to hearing impairment than other WS associated genetic pathogenic variations." (PMID 40868272, 2025). "Among the WS patients who participated in this study, all patients with SOX10 mutations have hearing loss, while some patients with PAX3 (3/7) or MITF (2/3) have." (PMID 34149797, 2021). "It is worth noting that NM_198159.2(MITF):c.1021C > T (p.Arg341Cys) was discovered from original file of an unreported VUS in patient 5, who presented only congenital profound hearing loss when they were referred for genetic testing." (PMID 31138263, 2019).
kidney cancer (10 papers, 2015 to 2025). Primary or metastatic malignant neoplasm involving the kidney. "The larger collection of non-type-I papillary RCCs is composed of type II papillary renal carcinomas, including duct carcinomas, medullary renal cell carcinomas, the MiTF kidney cancers (TFE3, TFEB), and hereditary leiomyomatosis RCC-associated kidney cancers." (PMID 33205131, 2020). "MITF is expressed in both melanocytes and the kidney, and a germline mutation in human MITF that predisposes to melanoma and kidney cancer has recently been found." (PMID 25670789, 2015). "TFEB and MITF mutations have also been noted in kidney cancers, albeit more rarely." (PMID 35358174, 2022). "A positive family history for kidney cancer was more frequent among MITF+ patients (18% versus 5% of MITF− patients; p = 0.01)." (PMID 32054529, 2020). "In addition, several genes, such as MITF, have been linked to kidney cancers but not to reduced kidney function or CKD." (PMID 36890159, 2023). "On the other hand, as overexpression of MITF/TFE family members is responsible for several types of cancer, including kidney cancer, it would be worthwhile to study the contribution of EGR1 to these cancers in vivo." (PMID 36888606, 2023).
melasma (10 papers, 2013 to 2025). "Some components of the Wnt/β-catenin pathway have been implicated in melasma as they affect MITF expression and activity, influencing melanocyte differentiation and melanin production." (PMID 39940926, 2025). "Pearl can alleviate melasma by targeting the CREB1/MITF axis and then the melasma‐related gene loci TYR and DCT." (PMID 40369904, 2025). "The potential mechanism of PE extract against melasma was predicted to target the CREB1/MITF/TYR/DCT axis." (PMID 40369904, 2025). "Here, we found that MITF overexpression can reverse the effects of pearl in melasma, suggesting the involvement of the MITF/TYR/DCT axis in the antimelasma mechanism of pearl." (PMID 40369904, 2025). "Inflammatory cytokines such as Tumor Necrosis Factor-alpha (TNF-α) modulate MITF expression and activity, contributing to the pathogenesis of melasma." (PMID 39940926, 2025). "Solar lentigo, PIH, and melasma, the most common UVR-associated hyperpigmentation disorders, are associated with increased MITF expression." (PMID 32226536, 2020). "We then further validated the CREB/MITF axis in PE against melasma using MITF overexpression." (PMID 40369904, 2025). "MITF and EDNRB2 are candidate genes associated with shin melanosis." (PMID 36011302, 2022). "MITF and EDNRB2 were the candidate genes associated with beak melanosis." (PMID 35886054, 2022). "Thus, controlling the expression of MITF in melanocytes by miRNAs may be beneficial for treating skin pigmentation disorders such as vitiligo and melasma." (PMID 32034251, 2020). "Melanocyte density measurement via MITF immunohistochemistry suggested the observed melanin content increase is due to increased melanin production and not increased number of melanocytes as only Melasma demonstrated an increase in density." (PMID 35677918, 2022).
metastatic disease (10 papers, 2010 to 2025). "In melanomas, early genomic studies found that MITF was amplified in metastatic disease and its increased expression correlated with decreased patient survival, suggesting that MITF is an oncogene." (PMID 32455885, 2020). "In fact, TFE3 negatively correlates with the expression of melanosomal genes in the metastatic tumors, indicating a specific role for MITF in regulating melanosomal genes." (PMID 30705290, 2019). "In terms of overall expression level, MITF had a 4- and 15-fold higher mRNA expression than that of TFEB and TFE3, respectively, in the metastatic tumors (Sup." (PMID 30705290, 2019).
prostate carcinoma (9 papers, 2016 to 2026). A carcinoma that arises from epithelial cells of the prostate gland. "The EMT-linked gene MITF (melanocyte inducing transcription factor) was subsequently shown to be a novel target of miR-182 in prostate cancer cells." (PMID 36768146, 2023). "In lethal prostate cancer, MITF functions as a transcriptional repressor of eukaryotic initiation factor 3B (eIF3B)." (PMID 41114928, 2025). "In sum, our study provides proof-of-concept evidence of the potential of the bioinformatics screen of publicly available cancer patient databases as discovery platforms, and demonstrates that the MITF-CRYAB axis controls prostate cancer biology." (PMID 30310055, 2018). "In summary, this is the first study to report that miR-182 over-expression in prostate cancer may contribute to EMT by targeting MITF expression." (PMID 36768146, 2023). "This evidence was supported by the enhanced prognostic potential of a signature based on the concomitant alteration of MITF and CRYAB in prostate cancer patients." (PMID 30310055, 2018). "In prostate cancer, miR‐182 high expression may contribute to EMT by targeting melanocyte‐inducing transcription factor (MITF) and promoting cancer progression." (PMID 39617640, 2024).
familial melanoma (8 papers, 2015 to 2025). Familial melanoma (FM) is a rare inherited form of melanoma characterized by development of histologically confirmed melanoma in two first degrees relatives or more relatives in an affected family. "While PVs have also been detected in several other genes, including CDK4, BAP1, ATM, MITF and multiple telomere stability genes TERT, POT1, ACD, and TERF21P, about half of the cases of familial melanoma remain unexplained." (PMID 40072281, 2025).
hepatocellular carcinoma (8 papers, 2017 to 2025). A malignant tumor that arises from hepatocytes. "MITF is overexpressed in hepatocellular and bile duct carcinoma, and has been associated with poor prognosis in hepatocellular carcinoma patients." (PMID 34208068, 2021). "Here we show that MITF is downregulated in PCa when compared with normal specimens, in contrast to the elevated expression reported in hepatocellular carcinoma and chronic myeloid leukemia." (PMID 30310055, 2018). "Notably, upregulated MCF2 and MITF expression was also observed in 21% and 33% of 24 human hepatocellular carcinomas analyzed." (PMID 29383183, 2017). "To date, except for MCL1 which has been proven by us and other literature studying hepatocellular carcinoma, among the validated miR-26a targets, HMGA1, PTEN, EZH2, MITF, DNMT3B, TGF-beta, and Ezh2 have been demonstrated to regulate chemoresistance." (PMID 33816494, 2021).
sarcoma (8 papers, 2011 to 2026). A usually aggressive malignant neoplasm of the soft tissue or bone. "However, PALB2 variant has been observed in the patient treated due to sarcoma who also carried the variants within PALB2 and MITF genes." (PMID 40040726, 2025). "It’s also hypothesized that the nuclear localization and activation of MITF/TFE3, caused by V-ATPase dysfunction, might contribute to GCT development, as TFE3 gene fusions and the nuclear presence of resulting fusion proteins are seen in various sarcomas." (PMID 39372871, 2024). "Interestingly, I.J. Davis group reported that TFEB can rescue MITF knockdown in cell sarcomas." (PMID 30634982, 2019).
mastocytosis (7 papers, 2015 to 2025). A clonal myeloproliferative neoplasm characterized by the proliferation and accumulation of neoplastic mast cells in one or multiple organs or organ systems. "In this study, we explored microphthalmia-associated transcription factor (MITF) and dependent targets in the context of mast cells and mastocytosis." (PMID 36834926, 2023). "Normally, expression of these miRNAs is involved in MITF suppression and inhibition of colony-forming capacity of mastocytosis cell lines." (PMID 33803981, 2021). "MITF is required for the transformed phenotype of mastocytosis." (PMID 37234172, 2023). "Because of the limited availability of mastocytosis patients and the reduced MCs numbers that can be obtained from the patient’s bone marrow, we used HMC-1 cells, a mast cell line harboring D816V as a cellular model of mastocytosis, to characterize MITF’s role further." (PMID 36834926, 2023). "MITF impairment reduces KIT expression in both GIST and HMC-1 cells—a cellular model of mastocytosis." (PMID 41168571, 2025). "In this study, we investigated miRNAs regulated by SH3BP2 silencing, the role of MITF activity, and the efficacy of MITF pathway inhibitor, ML329, in inhibiting the survival and cell proliferation in HMC-1 as a cellular model for mastocytosis." (PMID 36834926, 2023). "MITF expression is regulated by KIT-dependent signals and is required for the transformed phenotype of mastocytosis." (PMID 36834926, 2023). "Indeed, MITF expression is regulated by KIT-dependent signals and is required for the transformed phenotype of mastocytosis." (PMID 34066544, 2021).
multiple myeloma (7 papers, 2020 to 2024). "MITF serves as a critical mediator of senescence in melanocytes and myeloma cells, primarily by orchestrating processes like cell cycle regulation, DNA repair, oxidative stress response, and the production of SASP factors." (PMID 37886470, 2023). "It should be noted that knockdown of MITF by shRNA has been reported to promote apoptosis in multiple myeloma cells treated with dexamethasone." (PMID 33002292, 2020). "DeepIMAGER was applied to scRNA-seq datasets of multiple myeloma (MM) and detected potential GRNs for TFs of RORC, MITF, and FOXD2 in MM dendritic cells." (PMID 39062480, 2024). "When applied to scRNA-seq datasets of Multiple Myeloma (MM) patients, we identified potential regulations in GRNs of three TFs, RORC, MITF, and FOXD2 in dendritic cells, including many known regulations related to MM pathology." (PMID 39062480, 2024). "On the other hand, high expression levels of miR-137 have been observed in dexamethasone-treated multiple myeloma cells by targeting MCL-1 and MITF genes, thus inhibiting cancer cell proliferation and inducing apoptosis." (PMID 33670982, 2021).
angiomyolipoma (6 papers, 2013 to 2024). A neoplasm with perivascular epithelioid cell differentiation often associated with tuberous sclerosis. "Epithelioid angiomyolipoma is a rare variant of angiomyolipoma and a part of the microphthalmia transcription factor (MiTF) tumors." (PMID 36117733, 2022). "Likely germline alterations of BAP1, FLCN, and MITF were identified in 6.2% of cases after excluding benign renal neoplasia (oncocytoma and angiomyolipoma)." (PMID 34767027, 2021). "Indeed, MITF is considered a hallmark gene of lymphangioleiomyomatosis (LAM) and angiomyolipomas in TSC44,45, based on upregulation of genes that are known transcriptional targets of MITF/TFE3/TFEB/TFEC including MelanA and Cathepsin K46,47." (PMID 38195686, 2024). "Conversely, epithelioid angiomyolipoma will exhibit at least focal labeling for melanocytic markers, including HMB-45, melan-A, and MiTF, as well as usually diffuse labeling for cathepsin K." (PMID 29090117, 2017).
cardiac hypertrophy (6 papers, 2019 to 2024). "MITF (rs1430608) is expressed in the heart, and has previously been linked to beta-adrenergic-induced cardiac hypertrophy in mice and congenital heart disease in humans." (PMID 36376295, 2022). "A previous study has demonstrated that MITF regulates cardiac hypertrophy through targeting miR-541." (PMID 32104183, 2020). "A previous study has reported that MITF transcriptionally promotes GATA4 expression by binding to the E box in the GATA4 promoter in cardiac hypertrophy, responding to stress from ischemia." (PMID 32104183, 2020). "In addition to GATA, MEF2 and NFAT families, other transcription factors, such as UBF1 86, ATF3 87, T-Cdk9 88, XBP1 89, MITF 90, HSF1 91, C/EBP 92, KLF11 93 and KLF5/BTEB2 94 have been implicated in regulating cardiac hypertrophy." (PMID 39239522, 2024). "Although NFAT plays a central role in cardiac hypertrophy, the approach described here may be tested on further transcription factor targets involved in induction of cardiac hypertrophy, such as the MEF2, HAND, SFR or MITF genes." (PMID 34089101, 2021).
gastric cancer (6 papers, 2013 to 2025). A primary or metastatic malignant neoplasm involving the stomach. "This reduces MITF SUMOylation and subsequent RNF4‐mediated ubiquitination, leading to MITF protein accumulation and gastric cancer progression." (PMID 41114928, 2025). "In gastric cancer, CSE1L inhibition has been shown to activate the PI3K/AKT/mTOR and MEK/ERK pathways by downregulation of MITF and GPNMB." (PMID 39430746, 2024). "In conclusion, this study uncovered miR-585-5p impedes gastric cancer proliferation and metastasis by orchestrating the interactions among CREB1, MAPK1 and MITF." (PMID 36268034, 2022). "miR-876-5p targets WNT5A and MITF mRNA 3′UTR, represses the proliferation and migration ability of gastric cancer cells." (PMID 33542193, 2021).
glioblastoma (6 papers, 2015 to 2025). The most malignant astrocytic tumor (WHO grade IV). "Interestingly, GPNMB expression in melanoblasts and osteoclasts was shown to be dependent on MITF, and in human glioblastoma cells this transcription factor is activated by PI3K/Akt and GSK3β signaling." (PMID 25889792, 2015).
anaphylaxis (5 papers, 2019 to 2023). An acute hypersensitivity reaction that occurs from exposure to an allergen. "MITF is a potential immune response gene associated with the pathogenesis of IgE/MCs-mediated anaphylaxis." (PMID 38041124, 2023). "Recently, we identified that a mutation in LysRS (P542R) in a patient with severe anaphylaxis to wasp venom favors the recruitment of this molecule to the nucleus resulting in a constitutive increase in MITF activity." (PMID 37234172, 2023). "An increased MITF activity in mast cells has recently been associated with anaphylaxis." (PMID 36834926, 2023). "Previous studies have reported a central role for GATA-2 and MITF in CTMC differentiation and IgE-MC-mediated anaphylaxis." (PMID 31369572, 2019).
leukemia (5 papers, 2019 to 2021). A malignant (clonal) hematologic disorder, involving hematopoietic stem cells and characterized by the presence of primitive or atypical myeloid or lymphoid cells in the bone marrow and the blood. "On the previous basis, the expression of MiTF should be evaluated in other pathological situations in which BM fails, as well as in leukaemia, where its overexpression or loss-of-function may represent a driving force that allows the selection of clones bearing oncogenic mutations." (PMID 33441180, 2021). "However, when we compared Encode data for the K257 leukemia cell line using the GSM2527370 data for MITF and the GSM2700494 data for BRD4, we found 6937 MITF peaks and 8509 BRD4 peaks, with 1204 overlapping between MITF and BRD4." (PMID 32151278, 2020). "Histone deacetylase (HDAC)-inhibitor drugs could be considered for treatment in the clinical scenario of upregulated MITF and SETD2 inhibitors are currently being investigated in the treatment of leukemia." (PMID 31712784, 2019).
retinal degeneration (5 papers, 2016 to 2023). Degeneration of the retina. "Nevertheless, little is known about MITF’s potential involvement in the regulation of the visual cycle and whether the regulation of visual cycle genes by MITF contributes to retinal degeneration." (PMID 26876013, 2016). "We have previously shown that MITF regulates the expression of neurotrophic factors including PEDF in RPE cells, but whether Mitf-regulated neurotrophins play any role in retinal degeneration remains unknown." (PMID 30651300, 2019).
clear cell renal cell carcinoma (4 papers, 2020 to 2022). "However, the biological role of MITF in clear cell renal cell carcinoma (ccRCC) is largely unknown." (PMID 34208068, 2021). "However, the role of MITF in clear cell renal cell carcinoma (ccRCC) is largely unknown." (PMID 34208068, 2021). "Likewise, the proliferative defects induced by MITF knockout in an MITF-driven renal clear cell carcinoma model was restored by transfecting TFE3, indicating that MITF and TFE3 may have partially redundant roles in regulating proliferation and survival." (PMID 32881934, 2020).
desmoplastic melanoma (4 papers, 2021 to 2025). A melanoma of the skin characterized by a proliferation of atypical spindled melanocytes in the dermis, in a background of abundant collagen. "However, when diffuse MiTF staining is observed and evaluated in conjunction with clinical, histological, and other immunohistochemical findings, it can be diagnostically useful in select cases of desmoplastic melanoma." (PMID 40509563, 2025).
diabetes (4 papers, 2017 to 2022). "For instance, metformin, a drug used to treat diabetes, suppresses the expression of MITF and melanogenic genes by reducing cAMP/PKA/CREB signaling, thereby inhibiting melanin production in vivo and in human reconstituted epidermis." (PMID 36499416, 2022).
gastrointestinal stromal tumor (4 papers, 2022 to 2025). "Previously, our group established a relationship between the KIT receptor de-adaptor molecule SH3BP2 and the microphthalmia-associated transcription factor (MITF) in mast cells and gastrointestinal stromal tumors (GIST)." (PMID 36834926, 2023). "The role of Microphthalmia-associated Transcription Factor (MITF) in gastrointestinal stromal tumors (GISTs) remains unclear, although previous studies suggest it contributes to tumor growth regulation." (PMID 41168571, 2025). "We recently reported that silencing MITF impairs the survival and proliferation of gastrointestinal stromal tumors (GISTs)." (PMID 41168571, 2025). "Lately, we have described that the silencing of MITF results in decreased gastrointestinal stromal tumor cell viability in vitro and tumor growth in vivo." (PMID 36551682, 2022). "MITF inhibition suppresses the growth of imatinib-sensitive and resistant gastrointestinal stromal tumors (GIST) in established tumors in xenograft mouse models." (PMID 40343114, 2025).
neuroblastoma (4 papers, 2022 to 2025). Neuroblastoma (NB) is the most common solid, extracranial childhood tumor. "For example, we found a LP variant in MITF in a child with neuroblastoma." (PMID 37507557, 2023).